OMA1 (OMA1 zinc metallopeptidase)
Description:
Metalloprotease that is part of the quality control system in the inner membrane of mitochondria. Activated in response to various mitochondrial stress, leading to the proteolytic cleavage of target proteins, such as OPA1, UQCC3 and DELE1. Involved in the fusion of the mitochondrial inner membranes by mediating cleavage of OPA1 at S1 position, generating the soluble OPA1 (S-OPA1), which cooperates with the membrane form (L-OPA1) to coordinate the fusion of mitochondrial inner membranes. Following stress conditions that induce loss of mitochondrial membrane potential, mediates cleavage of OPA1, leading to excess production of soluble OPA1 (S-OPA1) and negative regulation of mitochondrial fusion. Involved in mitochondrial safeguard in response to transient mitochondrial membrane depolarization (flickering) by catalyzing cleavage of OPA1, leading to excess production of S-OPA1, preventing mitochondrial hyperfusion (By similarity). Also acts as a regulator of apoptosis: upon BAK and BAX aggregation, mediates cleavage of OPA1, leading to the remodeling of mitochondrial cristae and allowing the release of cytochrome c from mitochondrial cristae. In depolarized mitochondria, may also act as a backup protease for PINK1 by mediating PINK1 cleavage and promoting its subsequent degradation by the proteasome. May also cleave UQCC3 in response to mitochondrial depolarization. Also acts as an activator of the integrated stress response (ISR): in response to mitochondrial stress, mediates cleavage of DELE1 to generate the processed form of DELE1 (S-DELE1), which translocates to the cytosol and activates EIF2AK1/HRI to trigger the ISR. Its role in mitochondrial quality control is essential for regulating lipid metabolism as well as to maintain body temperature and energy expenditure under cold-stress conditions (By similarity). Binds cardiolipin, possibly regulating its protein turnover (By similarity). Required for the stability of the respiratory supercomplexes (By similarity).
Synonyms: MPRP-1; MPRP1; YKR087C; ZMPOMA1; FLJ33782; 2010001O09Rik; peptidase
Tractability: Antibody: UniProt predicts a signal peptide or a membrane-spanning region. PROTAC: ubiquitination databases record sites on it; its protein half-life has been measured.
Gene: Protein-coding gene on chromosome 1 (58,415,384 to 58,546,838, reverse strand). Ensembl gene ENSG00000162600.
Subcellular location: Mitochondrion inner membrane
Subcellular location (Human Protein Atlas): Mitochondria; Nucleoplasm
Pathways (Reactome):
Cellular responses to stimuli: Cellular response to mitochondrial stress
Metabolism of proteins: Mitochondrial protein degradation
Programmed Cell Death: Regulation of Apoptosis
Gene Ontology:
Molecular function: metalloendopeptidase activity
Biological process: cellular response to stress; HRI-mediated signaling; integrated stress response signaling; mitochondrial protein processing; negative regulation of mitochondrial fusion; positive regulation of apoptotic process; protein quality control for misfolded or incompletely synthesized proteins; regulation of cristae formation; diet induced thermogenesis; energy homeostasis; glucose metabolic process; lipid metabolic process; mitochondrial inner membrane fusion; mitochondrial respiratory chain complex assembly; positive regulation of cold-induced thermogenesis; protein autoprocessing; zymogen activation; proteolysis
Cellular component: mitochondrial inner membrane; mitochondrial intermembrane space; mitochondrial membrane; mitochondrion
Homologues: Orthologues: macaque OMA1 (93% identical), rabbit OMA1 (82% identical), dog OMA1 (81% identical), pig OMA1 (80% identical), guinea pig OMA1 (75% identical), mouse Oma1 (70% identical), rat Oma1 (69% identical), chimpanzee OMA1 (53% identical), tropical clawed frog oma1 (44% identical), zebrafish oma1 (41% identical).
Diseases named in the same sentence as OMA1 in open-access papers:
OMA1 is named in the same sentence as 65 diseases in open-access papers, as found by Europe PMC text mining. Sharing a sentence is not in itself a finding about the gene and the disease. The quoted sentences say what the papers report.
heart failure (8 papers, 2018 to 2024). Inability of the heart to pump blood at an adequate rate to meet tissue metabolic requirements. "The cardiac-specific activation of OMA1 and mitochondrial fragmentation causes heart failure, while OMA1 activation causes neuronal death in neurodegeneration and under ischemic injury in mouse models." (PMID 38674151, 2024). "All these suggested that the regulation of YME1L and OMA1 is potential target for preventing the progression of heart failure associated with distinct types of etiologies." (PMID 36093152, 2022). "Imbalanced OPA1 processing and mitochondrial fragmentation upon cardiac deletion of Yme1l are associated with cardiomyocyte death and heart failure, which can be suppressed by additional deletion of Oma1." (PMID 30389680, 2019). "OMA1 is an essential mediator of multiple etiologies of heart failure and a possible therapeutic target for maintaining myocardial integrity." (PMID 37559135, 2023). "Heart failure, cell death, and mitochondrial fragmentation can be rescued by knocking down Oma1 in mice." (PMID 37559135, 2023). "Ablation of OMA1 has been reported to protect against heart failure in multiple mouse models of mitochondrial dysfunction." (PMID 36290724, 2022). "Furthermore, inhibition of OMA1 protects the heart against heart failure in response to multiple types of cardiac insult by preventing crista remodeling." (PMID 37798455, 2023). "Ablation of OMA1 was previously found to protect against heart failure in multiple mouse models of mitochondrial dysfunction, which might be mediated by attenuation of ISR." (PMID 36290724, 2022). "Acin-Perez demonstrated that OMA1 ablation averts cardiomyocyte death in three different mouse models of heart failure: tachycardiomyopathy, heart failure with preserved left ventricular ejection fraction, and left ventricular myocardial ischemia and hypertrophy." (PMID 36093152, 2022). "In various disease models, such as heart failure, kidney ischemia, or neurodegenerative diseases, OMA1-mediated cleavage of OPA1 at the S1 site does not cause mitochondrial fusion." (PMID 35395832, 2022). "Additionally, increased levels of mitochondrial ROS were shown to be causal for cristae disruption and cardiac pathology in mouse models of heart failure, and KO of OMA1 decreased heart failure pathology." (PMID 30544804, 2018). "Deletion of Oma1 restored tubular mitochondria and suppressed cardiomyocyte death and heart failure in the absence of YME1L." (PMID 30389680, 2019).
cardiomyopathy (6 papers, 2023 to 2025). A disease of the heart muscle or myocardium proper. "As OXPHOS deficiency also induces Opa1 processing by Oma1 in vivo, we investigated the role of Opa1 processing in cardiomyopathy associated with OXPHOS dysfunction." (PMID 39093974, 2024). "Indeed, whole‐body deletion of Oma1 has been linked to obesity, reduced thermogenesis, and aggravation of cardiomyopathy in rodent studies." (PMID 41388823, 2025). "Importantly, G58R mice recapitulate key elements of the disease such as myopathy, cardiomyopathy, mitochondrial cristal dilations and OMA1 activation." (PMID 37815936, 2023). "Impairing GPX4 upregulation induced by OXPHOS deficiency through the inhibition of the integrated stress response, by knocking out either the mitochondrial protease OMA1 or its substrate DELE1, aggravates the cardiomyopathy of Cox10-/- mice by decreasing GPX4 to WT levels, thus inducing ferroptosis." (PMID 37505079, 2023).
Obesity (6 papers, 2018 to 2025). Accumulation of substantial excess body fat. "OMA1-deficient mice display a diet-induced obesity phenotype, with increased hepatic steatosis and alteration of glucose metabolism, in addition to defective thermogenesis, suggesting a role for OMA1 in energy metabolism." (PMID 33078210, 2021). "Deficiency of Oma1 leads to increased body weight and fat contents, as well as impaired thermogenesis after diet-induced obesity in mice." (PMID 30307158, 2018). "Moreover, OMA1-mediated OPA1 processing is essential for fully activation of BAT thermogenesis, and loss of OMA1 results in obesity and defective thermogenesis." (PMID 37816711, 2023). "However, Oma1-deficient mice lost these metabolic benefits in the condition of high-fat diet-induced obesity." (PMID 30307158, 2018). "Oma1−/− mice show increased diet-induced obesity and altered thermogenesis during cold stress." (PMID 39093974, 2024). "The deficiency of Oma1 perturbs the mitochondrial fusion–fission equilibrium, thereby reducing OXPHOS, enhancing fatty acid oxidation and decreasing energy expenditure, all of which collaboratively induce obesity in mice." (PMID 31551926, 2019).
breast carcinoma (3 papers, 2019 to 2024). "Loss of OMA1 expression significantly promoted the EMT of breast cancers with a decrease in the epithelial markers and an increase in the mesenchyme markers." (PMID 31611601, 2019). "They found that OMA1 deficiency increases the proliferation and invasion of breast cancer cells." (PMID 39487118, 2024). "To determine if OMA1 expression was related to patient prognosis, we performed survival risk prediction using survival database to evaluate the correlation between OMA1 expression levels and overall survival rates in breast cancer patients." (PMID 31611601, 2019). "Silencing OMA1 in vitro in metastatic breast cancer cells increases cell proliferation and induces an epithelial–mesenchymal transition (EMT)." (PMID 37445598, 2023). "These clinical data demonstrates that attenuated OMA1 levels in human breast cancer patients are correlated to the molecular gene signatures buttressing EMT, a well-established hallmark of invasion/metastasis." (PMID 31611601, 2019). "We show that low expression of mitochondrial quality control protease OMA1 correlates with poor overall survival in breast cancer patients." (PMID 31611601, 2019). "To further interrogate the intriguing link between OMA1 silencing and the observed enhancement of cellular migration, we examined the migratory potential of the metastatic breast cancer cells with normal and reduced levels of the protease." (PMID 31611601, 2019). "To better understand the involvement of OMA1 in breast cancer, we next determined the survival of subjects in the low and high OMA1 expressing subsets." (PMID 31611601, 2019). "Overall, these results suggest a plausible role of OMA1 in suppressing aggressiveness and metastatic potential of these breast cancer cells." (PMID 31611601, 2019). "To further extend these findings in other cancer cells, we generated stable knockdowns of OMA1 in patient-derived breast cancer cells isolated from atypical ductal hyperplasia (21PT) using OMA1-specific shRNAs." (PMID 31611601, 2019). "Consistent with enhanced metastatic abilities of the OMA1-depleted breast cancer cells, we observed a significant upregulation of mesenchymal markers and decreased expression of epithelial markers at both the gene and protein levels." (PMID 31611601, 2019). "Lower expression of OMA1 correlates with poor overall survival in breast cancer patients." (PMID 37445598, 2023). "In conclusion, we report that down regulation of OMA1 expression in metastatic breast cancer cells and the subsequent activation of UPRmt could form the basis for promoting malignancy and metastatic progression of breast adenocarcinoma." (PMID 31611601, 2019). "Importantly, to the best of our knowledge, this is the first study that has evaluated the clinical value of OMA1 in breast cancer, particularly in the context of EMT process." (PMID 31611601, 2019). "An important finding of the present study is the impact of OMA1 on EMT in breast cancers." (PMID 31611601, 2019). "To that end, we used GEPIA (Gene Expression Profiling Interactive Analysis), a web-based tool (uses TCGA and GTEx dataset) to determine the relationship between aberrant OMA1 mRNA levels with the expression of some of the common EMT marker genes in human breast cancer." (PMID 31611601, 2019). "Elucidation of the exact role of OMA1 in regulating tumor biology and steps of EMT will help in the development of improved anti-metastatic therapies that are useful against circulating metastatic breast cancer cells and drug resistant cancer cells." (PMID 31611601, 2019). "To test this hypothesis, we generated stable knockdowns of OMA1 in non-tumorigenic breast epithelial cells (MCF10A) and patient-derived breast cancer cells isolated from metastatic pleural effusion mammary tumor specimen (21MT-1) cells using OMA1-specifc shRNAs." (PMID 31611601, 2019).
colorectal cancer (3 papers, 2024 to 2025). A primary or metastatic malignant neoplasm that affects the colon or rectum. "Consistently, OMA1 is upregulated under hypoxia and contributes to colorectal cancer development by promoting glycolysis, and OMA1 deficiency reduces colorectal cancer growth." (PMID 39487118, 2024). "In a colorectal cancer model, OMA1 promoted a shift towards glycolysis via HIF‐1α stabilization, effectively suppressing OXPHOS in favor of glycolytic ATP production." (PMID 41388823, 2025). "As OMA1 is pro-apoptotic through OPA1 processing, the inhibition of OMA1 promotes glycolytic metabolism and tumor progression in colorectal cancer, while activating OMA1 increases chemotherapeutic effectiveness in ovarian cancer settings." (PMID 38674151, 2024).
diabetic kidney disease (3 papers, 2021 to 2026). Progressive kidney disorder caused by vascular damage to the glomerular capillaries, in patients with diabetes mellitus. "The peptide SS31, which was associated with decreased levels of OMA1, has alleviated glomerular disease and restored OXPHOS in a mouse model of diabetic kidney disease with mitochondrial dysfunction." (PMID 41509918, 2026). "In a rodent diabetic nephropathy model, treatment with the mitochondria‐targeted peptide SS31 reduced OMA1 levels, restored mitochondrial function, and mitigated podocyte injury." (PMID 41388823, 2025).
dilated cardiomyopathy (3 papers, 2023 to 2025). Cardiomyopathy which is characterized by dilation and contractile dysfunction of the left and right ventricles. "Specific ablation of cardiac Yme1L in mice to activate OMA1 accelerates OPA1 proteolysis, triggering mitochondrial fragmentation and altering cardiometabolic, leading to dilated cardiomyopathy." (PMID 37603376, 2023).
ischemia (3 papers, 2018 to 2022). A hypoperfusion of the BLOOD through an organ or tissue caused by a PATHOLOGIC CONSTRICTION or obstruction of its BLOOD VESSELS, or an absence of BLOOD CIRCULATION. "The levels of OPA1, OMA1, and YME1L1 in the brain tissue surrounding the ischemia were detected by western blot and immunofluorescence staining in the adjacent section of TTC staining." (PMID 35395832, 2022). "Studies have showed that OMA1 activation made all long form of OPA1 cleaved, thereby disrupting the balance of long and short forms, which involved in ischemia-induced tissue injury of kidney and brain in animal models." (PMID 30046376, 2018).
ovarian carcinoma (3 papers, 2022 to 2024). A malignant neoplasm originating from the surface ovarian epithelium. "In summary, the breakdown of the PHB2/STOML2 complex promotes apoptosis of ovarian cancer cells through the mitochondrial PHB2/OMA1/DELE1 pathway." (PMID 37190120, 2023). "Activation of OMA1, a mitochondrial protease, was shown to increase ovarian cancer sensitivity to cisplatin, both in vitro and in vivo." (PMID 37190120, 2023). "Exploring the regulation of OMA1 by the PHB2/STOML2 complex will help to illustrate a potential mechanism of targeting mitochondria to increase the chemosensitivity of ovarian cancer cells." (PMID 35163244, 2022). "In the process of ovarian cancer cell apoptosis, L-OMA1 (60 KDa) accumulated and S-OMA1 (40 KDa) disappeared, indicating that OMA1 activation promoted apoptosis." (PMID 35163244, 2022). "Mechanistically, in ovarian cancer, OMA1 cleaved optic atrophy 1 (OPA1), leading to mitochondrial inner membrane cristae remodeling." (PMID 35163244, 2022). "Collectively, OMA1 coordinates the mitochondrial inner and outer membranes to induce ovarian cancer cell death." (PMID 35163244, 2022). "We found that OMA1 activation increased ovarian cancer sensitivity to cisplatin in vivo and in vitro." (PMID 35163244, 2022). "Although OMA1 is not the primary cause of ovarian cancer, its activation is involved in the apoptosis of ovarian cancer cells." (PMID 35163244, 2022). "Therefore, we evaluated the effect of OMA1 on the response to chemotherapeutics in ovarian cancer cells and the mouse subcutaneous tumor model." (PMID 35163244, 2022). "Understanding the role of OMA1 in ovarian cancer may help to explain the mechanism of anticancer agents on mitochondrial-mediated apoptosis." (PMID 35163244, 2022). "This study provides new insights into the role of OMA1 in the coordination of mitochondrial inner and outer membranes in ovarian cancer and indicates that OMA1 could be a potential target for the treatment of ovarian cancer." (PMID 35163244, 2022). "Thus, activating OMA1 may be a novel treatment strategy for ovarian cancer." (PMID 35163244, 2022). "Nevertheless, a role for OMA1 in ovarian cancer has not been established." (PMID 35163244, 2022). "Collectively, our results showed that the mitochondrial PHB2/OMA1/DELE1 pathway cooperated with cisplatin-induced ER stress to amplify the pro-death signals of MIM and MOM, which provided a novel mechanism for increasing the sensitivity of ovarian cancer to cisplatin." (PMID 35163244, 2022).
acute kidney injury (2 papers, 2025 to 2026). Sudden and sustained deterioration of the kidney function characterized by decreased glomerular filtration rate, increased serum creatinine or oliguria. "Similarly, hyperoside, a compound derived from Abelmoschus manihot flowers, alleviated adriamycin-induced podocyte injury as well as ischemia/reperfusion-induced acute kidney injury in mice by acting as an OMA1 inhibitor." (PMID 41509918, 2026). "Likewise, in acute kidney injury models, OMA1 activation was shown to exacerbate kidney injury, and inhibition of OMA1 rescued renal function and protected proximal tubular cells from apoptosis." (PMID 41388823, 2025).
cardiac hypertrophy (2 papers, 2022 to 2024). "Regardless, our results reveal an intriguing regulatory circuit linking Opa1 processing to cardiac hypertrophy and highlight the role of Oma1 as a stress-protective protease in heart disease." (PMID 39093974, 2024). "Thus, the requirement of Oma1-mediated Opa1 processing for cardiac hypertrophy is independent of mitochondrial stress signaling." (PMID 39093974, 2024). "A large number of genes (at least 19) related to mitochondria or energy production, such as Oma1 and COQ7, were found to have genetic interactions with ATE1 through GO term studies, and those partial proteins have been reported to be involved in the regulation of cardiac hypertrophy." (PMID 35341136, 2022).
diabetes (2 papers, 2018 to 2023). "Amidst the subset of DEGs, the prominent gene signatures include INS, INSR, DNAJC3, OMA1, GOS2, and CALR which have been reported to be differentially expressed in type 2 diabetes mellitus and/ or metabolic disorders." (PMID 37943808, 2023).
glioblastoma (2 papers, 2024 to 2026). The most malignant astrocytic tumor (WHO grade IV). "On the other hand, the TCGA database shows that in certain tumors, such as gastric cancer, esophageal carcinoma, glioblastoma multiforme, squamous cell carcinoma of the cervix, and endocervical adenocarcinoma, the expression of OMA1 is relatively high in comparison with that in normal tissues." (PMID 39487118, 2024). "In glioblastoma, HSPA9 interacts with OMA1 zinc metallopeptidase (OMA1) and induces mitophagy." (PMID 41491061, 2026).